NRAS (NRAS proto-oncogene, GTPase)
Diseases named in the same sentence as NRAS in open-access papers (continued):
Sharing a sentence is not in itself a finding about the gene and the disease.
tumor (continued). "We confirmed substantial NRAS gene amplification in the CUTO44 cell line using NRAS FISH probes and observed an average of 21 copies of NRAS per cell and an NRAS/CEP1 ratio of 3.4, and NRAS amplification was not present in the patient tumor sample biopsied prior to crizotinib therapy." (PMID 34642436, 2021). "Additionally, we found that the status of Fusobacteria was associated with the age of the patients, tumor diameter, and MSI status, but not with genetic mutations in KRAS, NRAS, BRAF, and PIK3CA." (PMID 34650531, 2021). "While WT RAS of the same isoform generally inhibits tumor initiation and growth, the protein products of the two non-mutated, WT RAS genes (for example HRAS and NRAS in a KRAS-mutated cancer; hereafter called WT RAS in all cases) are tumor promoting in RAS-mutated tumors." (PMID 33924994, 2021). "However, we found no statistically significant concordance in any BRAF, KRAS, NRAS, and TERT promoter mutation between the tumor tissue versus plasma, and the metastatic lymph node versus plasma." (PMID 33915745, 2021). "The difference between the 20–29 and 40 and over age groups was significant (p = 0.032), but became non-significant when adjusted for tumor type (p = 0.25) Both KIT and NRAS mutations were about twice as common among older-onset tumors than the two young-onset groups." (PMID 34819066, 2021). "However, no NRAS clone was detectable in the tumor prior to IT, suggesting its emergence after therapy." (PMID 34072863, 2021). "Additionally, it was found that the abundance of Fusobacteria in CRC tumor tissues was associated with MSI status, but not KRAS, NRAS, BRAF, and PIK3CA gene status." (PMID 34650531, 2021). "Considering the small number of patients, the association between the expression of SK1 and the tumor stage, the mutation status of BRAF and NRAS, as well as immune responses could not be performed due to weak statistical power in this retrospective study." (PMID 31974367, 2020). "From 1979, cellular ras sequences with transforming properties were identified by transfection of tumor DNA initially by Robert Weinberg from rodent tumors, and the isolation of homologous oncogenes from human tumors soon followed, including HRAS and KRAS, and a new member of the family named NRAS." (PMID 32728828, 2020). "The tumour mutational profile identified no mutations in the KRAS, NRAS or BRAF genes." (PMID 32899374, 2020). "Since the levels of MAPK activation may be significantly different between tumours with low vs high mutant NRAS VAF, we assessed the correlation between NRAS VAF where available and MEK 6 gene score and found a modest positive correlation (Pearson’s correlation coefficient, r = 0.51)." (PMID 31839677, 2020). "Finally, comparing tumor DNA results, 24 patients with BRAF, KRAS and NRAS mutations had shorter survival than 33 patients without these mutations (25 months vs. 61months, P=0.0334)." (PMID 32284750, 2020). "We could not demonstrate any relation of NRAS mutant status to HT etiology, papillary morphology or multifocality of the tumor." (PMID 30666518, 2019). "Four of the five upregulated RMGs (CTNNB1, EGFR, NRAS, and KIT) were oncogenes and 12 of the 32 downregulated RMGs were tumor suppressor genes, which was consistent with the increased expression of oncogenes and decreased expression of tumor suppressor genes in tumor development." (PMID 30107644, 2018). "Similarly, in the second patient, inference of clones from the bulk sequencing data failed to predict the presence of the IDH2 (R140Q), NRAS (G13R) double-mutant clone comprising ∼30% of the total tumor population." (PMID 30087104, 2018). "Demographics and baseline characteristics were well balanced between patients with mutant tumours (i.e., KRAS/NRAS mutation in tissue and/or KRAS mutation in blood, n = 92) and those with wild-type tumours (i.e., neither KRAS/NRAS mutation in tissue nor KRAS mutation in blood, n = 30)." (PMID 29362371, 2018).
tumor (continued). "Thanks to next generation sequencing (NGS) and circulating tumor DNA (ctDNA) studies, the authors also showed the mechanisms of resistance to anti-EGFR drugs, such as the presence of EGF-R negative tumor clones, KRAS mutation/amplifications, PTEN deletion, and NRAS/HER2/MYC amplifications." (PMID 30205505, 2018). "We identified seven oncogenes (NRAS, EGFR, RXRA, HRAS, KRAS, AKT1, ERBB2; q<0.10) and seven putative tumor suppressor genes (ARID1A, TXNIP, CTNNB1, PIK3RI, CDKN2A, KLF5, STAG2; q<0.10) significantly regulated between tumor and control, which were formerly reported to be altered in BC." (PMID 30419021, 2018). "The molecular differences in BRAF and NRAS mutations and CIMP-high and gene expression in tumor sidedness may account for this since the effect of primary tumor location was not significant on multivariate analysis." (PMID 30296945, 2018). "Notably, the IDH2 (R140Q) NRAS (G13R) clone was not predicted from the bulk sequencing VAFs, yet it represented 29% of the diagnosis tumor defined by single-cell DNA sequencing." (PMID 30087104, 2018). "Although this correlation was not confirmed in our collective, NRAS-mutant tumors accounted for 4 out of 6 local relapses at the primary tumor site and loco-regional recurrence and distant metastasis were significantly more commonly observed in NRAS-mutant patients." (PMID 28797232, 2017). "Moreover, silencing and overexpression of NRAS across different cancer cell lines selectively impacted metastatic capacity to the lungs, but not primary tumor growth." (PMID 28341702, 2017). "Since they typically do not coexist in the same tumor, it is possible that mutations in KRAS and NRAS genes are functionally redundant as they could provide similar or identical oncogenic signals." (PMID 27636997, 2016). "Two tumours (FTC No. 1 and PTC No. 22) showed NRAS (c.2987A>G, p.Q61R) mutations." (PMID 22675538, 2012). "Moreover, important molecular markers, such as KRAS, NRAS, and BRAF mutations, could not be evaluated, thereby restricting the ability to analyze the impact of tumor biology on survival comprehensively." (PMID 41517497, 2025). "Consequently, we speculate that in the high PRTFDC1 expression group, tumor cells may be more reliant on the purine nucleotide salvage pathway to promote proliferation, rather than on the signaling pathways activated by KIT, NRAS, or KRAS mutations." (PMID 40241724, 2025). "These mutations may occur in receptors (e.g., KITKIT), effectors (BRAF, NRAS), or inhibitors (NF1, RASA2, CDKN2A, SPRED1) of the pathway, leading to proliferation of transformed melanocytes, abnormal differentiation, and persistent survival with impaired apoptosis of tumour cells." (PMID 41295253, 2025). "Additionally, an NRAS variant was detected at a very low allele fraction, raising the possibility of it being a clonal hematopoiesis of indeterminate potential (CHIP) rather than a true tumor mutation." (PMID 40526090, 2025). "Notably, several mutations (5× BRCA2, 4× ERBB2, 2× NRAS, 2× HCN1 [hyperpolarization-activated cyclic nucleotide-gated potassium channel 1]) were detected more than once in plasma or stool samples across all patients but never in tumor biopsies." (PMID 38766867, 2024). "The differential features in the HCC clones with the same AKT1/NRAS integration sites may be due to the intratumoral differentiation and in vitro selection of the HCC clones originated from the same transformed hepatocyte which gained growth advantage in the very beginning of tumor progression." (PMID 35721518, 2022). "Consequently, inhibition of FAK may provide a reasonable and tumor selective strategy to sensitize MM to cell death, irrespective of their BRAF/NRAS mutation status." (PMID 35022419, 2022).
tumor (continued). "Patient triage could be performed by a quick assessment of tumor burden and testing of biomarkers with predictive and prognostic value (such as immunohistochemistry for mismatch repair proteins; sequence variation analysis for KRAS [GenBank 3845], NRAS [GenBank 4893], and BRAF)." (PMID 34495337, 2021). "Thus, PIK3CA, NRAS, HRAS, PTEN, MET, and IDH2 R140Q mutations might be related to the metastasis process rather than primary tumor development." (PMID 29290998, 2017). "All the data suggest a lack of linear relationship between tumor cell percentage and mutant VAFs in BRAF, KRAS, and NRAS in CRC." (PMID 38397405, 2024). "Neither BRAF nor NRAS showed any statistically significant correlation between VAF and tumor cellularity." (PMID 38397405, 2024). "It has been demonstrated that the expression of biomarkers such as KRAS, NRAS, and BRAF, in conjunction with the MSI state of the tumour, serves as a negative predictor for anti-EGFR therapy in mCRC patients." (PMID 36612217, 2022). "Another option is the use of agents that do not target the BRAF, NRAS, or MEK/ERK pathway at all, but inhibit essential mechanisms (such as antiapoptosis) important for tumor growth." (PMID 34063141, 2021). "Their effect on anchorage-independent growth, which is of significant importance in tumour biology, was summarised as follows: KRAS4A >/= NRAS >>> KRAS4B = HRAS = no growth." (PMID 32772213, 2020). "The circulating NRAS mutations split the metabolic groups, and the IDH1 mutation was only found in Patient 3, however, it cannot be ruled out that a more detailed genomic analysis of the tumour itself could have revealed additional mutations which correlated with the metabolic changes observed." (PMID 31795195, 2019). "In reality, the REB array can be used to exclude tumours with common BRAF or NRAS mutations from further testing, allowing resources to be concentrated on sequencing cases where the driver mutation is not known, and knowledge of the KIT status of the tumour may be helpful." (PMID 28228113, 2017). "No other significant correlations between KRAS or NRAS mRNA expression and gender, AJCC stage, tumor thickness, or ulceration were found." (PMID 29349077, 2017). "Interestingly, CD38 targeting did not significantly alter the in vivo growth of NRAS;Ink4a lesions, but the combination of anti-CD38 (αCD38)/αPD-1 significantly reduced tumor growth." (PMID 40530504, 2025). "Similar to NRAS(G12V)-N1ICD-driven tumours, early-onset tumours with DS3–4 were mostly positive for nestin and NOTCH1, whereas the majority of late-onset differentiated tumours (DS1–2) were negative for nestin/NOTCH1." (PMID 39112713, 2024). "By contrast, Dlk1+ cells were detected in all tumours irrespective of time of onset (n = 15) but retained their hepatocytic morphology and were spatially distinct from NOTCH1/nestin+ regions, where Dlk1+ cells tended to exhibit lower NRAS expression." (PMID 39112713, 2024). "However, Dnmt1 re-expression in Sox9 CKO livers slightly but significantly restored tumor formation driven by Akt-NRAS, but not Akt-YAP1, implying the partial involvement of Dnmt1 in Akt-NRAS tumor development under the SOX9." (PMID 39273023, 2024). "Notably, upregulated genes in relapsed SW837 xenograft tumor included MRAS, a homologue of the RAS family of GTPases37, and RasGRP1, a Ras GEF38,39, but not NRAS or HRAS." (PMID 39103541, 2024).
tumor (continued). "Mutations affecting specific codons (so-called “hot-spot” codons) in exons 2, 3 and 4 of the KRAS and NRAS genes have been identified, which predict non-response to anti-EGFR mAbs and allow the further malignant proliferation of tumour cells, despite treatment." (PMID 27784278, 2016). "As such, the effects of NRAS/BRAF status on survival may reflect an enhanced effect of treatment or, alternatively, tumor biology independent of drug therapy." (PMID 23673558, 2013).
cancer (815 papers, 2004 to 2026). A tumor composed of atypical neoplastic, often pleomorphic cells that invade other tissues. "Mutations in RAS oncogenes (KRAS, HRAS, NRAS) are among the most common genetic alterations in human cancers." (PMID 41822354, 2026). "Oncogenic KRAS and NRAS mutations are common in hematologic malignancies, but how they signal is less well characterized than in carcinomas." (PMID 41542462, 2026). "KRAS and NRAS were mainly altered by mutually exclusive canonical hotspots of missense mutations described in carcinomas." (PMID 41057685, 2026). "Only three studies, with 3271 cancer patients and 89 NRAS-mutant individuals, analyzed the association between NRAS mutation status and survival." (PMID 40279317, 2025). "NRAS mutations are frequently observed in melanomas and certain hematopoietic malignancies, while HRAS mutations are prevalent in head and neck cancers." (PMID 40906088, 2025). "The striatal clone contained additional cancer-associated driver mutations (NRAS G12D and DNMT3A splice donor variants)." (PMID 40610627, 2025). "These aspects are a challenge to the penetration of PDAC and delivery of therapies, such as antibodies.The RAS protein is frequently mutationally activated (HRAS, KRAS, and NRAS) in human cancer." (PMID 40002297, 2025). "This analysis involved data for responses to reduced NRAS-mRNA levels of more than one thousand cell lines, covering over 30 different cancer types (specifically CRISPR mediated loss-of-function data from 1150 cell lines and RNAi data from 710 cell lines)." (PMID 40473796, 2025). "Since its discovery in neuroblastomas in 1983 and its characterization as an oncogene, various mutations in NRAS have been identified in many types of cancer." (PMID 39941834, 2025). "It was observed that cancers carrying the NRAS mutation differ in their Peroxisomal Biogenesis Factor 1 (PEX1) expression that was reported to be crucial for generation of lipids with polyunsaturated acids making them sensitive to oxidation." (PMID 40382332, 2025). "An evaluation of 6876 cancer samples with NRAS mutations from the COSMIC database found that 23% had a G12 mutation." (PMID 39941834, 2025). "Oncogenic NRAS mutations have shown to regulate cancer cell proliferation, metastasis, and response to targeted therapies and chemotherapy by modulating several oncogenic signaling pathways such as MAPK pathway, PI3K-AKT signaling pathway among others." (PMID 38982514, 2024). "Among different RAS isotypes, KRAS is the prevalent mutation associated with different types of cancer, namely, pancreatic, colorectal, and lung carcinoma, while the incidence of NRAS and HRAS mutation is less among these three types of cancer." (PMID 39056802, 2024). "The BAY 11-7082 treatment exerts a broad-spectrum impact, mechanistically altering various pathways in cancer cells harboring NRAS, KRAS, and HRAS mutations." (PMID 38982514, 2024). "The allelic model revealed an association between the minor allele T of NRAS rs14804 and advanced stages of cancer (OR 5.235; 95% CI: 1.492-15.709; p = 0.019)." (PMID 39867023, 2024). "The RAS genes which code for KRAS, HRAS, and NRAS are three of the most frequently mutated oncogenes responsible for cancer deaths." (PMID 39184150, 2024). "The RAS pathway is involved in cell signaling, and mutations in NRAS can lead to aberrant activation of this pathway, contributing to the pathogenesis of certain cancers." (PMID 38363781, 2024). "Today, it is well known that mutations in BRAF or NRAS are the drivers of up to 70% of human cancers, and therapies that target this pathway have been developed." (PMID 38299666, 2024). "We subsequently evaluated BAY 11-7082’s efficacy in inhibiting the tumorigenic potential of cancer cells expressing oncogenic NRAS, KRAS, and HRAS mutations." (PMID 38982514, 2024).